MALAT1 (metastasis associated lung adenocarcinoma transcript 1)
Diseases named in the same sentence as MALAT1 in open-access papers (continued):
Sharing a sentence is not in itself a finding about the gene and the disease.
cancer (continued). "In recent studies, lncRNAs such as metastasis-associated lung adenocarcinoma transcript 1 (MALAT1) have been shown to participate in cancer progression." (PMID 34012919, 2021). "Others have been implicated in diseases such as cancer, including metastasis associated lung adenocarcinoma transcript 1 (MALAT1) and plasmacytoma variant translocation 1 (PVT1)." (PMID 34940760, 2021). "Among the identified lncRNAs, HOX transcript antisense RNA (HOTAIR) and metastasis associated in lung adenocarcinoma transcript 1 (MALAT1) are the best characterized examples in cancer progression regulation." (PMID 34842045, 2021). "Metastasis-associated lung adenocarcinoma transcript 1 (MALAT1) is a well-known lncRNA, shown to be either downregulated or upregulated in different types of cancers." (PMID 34771513, 2021). "Three thyroid-specific genes (TG, TPO, and NIS), six cancer-associated lncRNAs (MALAT1, NEAT1, HOTAIR, H19, PVT1, MEG3), and two housekeeping genes (GAPDH and P0) were analyzed using Droplet Digital PCR (ddPCR)." (PMID 33030666, 2021). "MALAT1 upregulation is closely associated with the development of cancers such as lung, glioblastoma, esophageal squamous cell carcinoma, renal cell carcinoma, colorectal cancer, osteosarcoma, multiple myeloma, gastric cancer (Zhang YF." (PMID 34899344, 2021). "In EOC, lncRNA metastasis-associated lung adenocarcinoma transcript 1 (MALAT1) from cancer cells can be transferred to HUVECs via exosomes." (PMID 34819615, 2021). "MALAT1 encoded a bona fide long noncoding RNA and was previously identified as a prognostic marker for cancer metastasis." (PMID 33589441, 2021). "For instance, studies have shown the lncRNA MALAT1 to be associated with the development and metastasis of cancer cells." (PMID 34630508, 2021). "Metastasis-associated lung adenocarcinoma transcript 1 (MALAT1) is one of the best-described lncRNAs and its up-regulation has been associated with progression and chemoresistance in different types of cancers." (PMID 35052757, 2021). "We utilized a lncRNA array dataset (GSE81034) to analyze the expression of well-known, cancer metastasis-associated lncRNAs (i.e., MALAT-1, NEAT-1, HOTAIR, and HOXA11-AS) in the five cell lines by comparing exosomal RNA versus total RNA." (PMID 33514011, 2021). "Various signaling pathways are involved in EMT and accumulating data demonstrates that metastasis-associated lung adenocarcinoma transcript 1 (MALAT1) is capable of induction of EMT in a number of cancers leading to their high invasion capability." (PMID 33478512, 2021). "MALAT1, a lncRNA that is upregulated in different solid and hematological tumors and that has been associated with cancer metastasis and recurrence, seems to be involved in chemotherapy sensitivity in DLBCL cell lines by enhancing autophagy-related proteins." (PMID 33593440, 2021). "The underlying molecular mechanism involves direct binding of MALAT1 to miR-195, a suppressor of PD-L1 mRNA translation, thus allowing overexpression of PD-L1 on cancer cells." (PMID 34943820, 2021). "lncRNA MALAT1 (Metastasis-Associated Lung Adenocarcinoma Transcript 1) plays a vital role in the developmental stages of various cancer types as liver cancer and renal carcinoma." (PMID 33522932, 2021). "Previous studies have reported the association of the serum expression of NEAT1 and MALAT1 with several types of cancer." (PMID 33670447, 2021). "Among these LncRNAs, metastasis-associated lung adenocarcinoma transcript 1 (MALAT1) was commonly considered as a target for antimetastatic therapy in cancer, which is associated with solid tumor progression." (PMID 34221014, 2021).
cancer (continued). "One notable cancer-associated lncRNA is human metastasis-associated lung adenocarcinoma transcript 1 (MALAT1), whose longest isoform has over 8700 nucleotides and its mature form terminates in a triple helix at its 3′ end." (PMID 33450947, 2021). "Metastasis-associated lung adenocarcinoma transcript 1 (MALAT1) was a conserved lncRNA that was upregulated in multiple types of cancers." (PMID 34745970, 2021). "Among the first cancer-associated lncRNAs to be identified was MALAT1, also known as nuclear enriched abundant transcript 2 (NEAT2)." (PMID 34940760, 2021). "Metastasis Associated Lung Adenocarcinoma Transcript 1 (MALAT1) is one of the most widely studied lncRNAs in cancer therapy." (PMID 34758879, 2021). "The diagnostic and prognostic significance of MALAT1 has been demonstrated in gliomas and different cancers of the breast, lung, ovary, pancreas, and prostate." (PMID 33927753, 2021). "This work allowed identifying three new cancer susceptibility candidate lncRNAs in dogs, which are well-described in human cancer, including MALAT1, that is associated with human VM and metastasis." (PMID 34631854, 2021). "In particular, we analyzed, by Droplet Digital PCR (ddPCR), six cancer-associated lncRNAs (MALAT1, NEAT1, HOTAIR, H19, PVT1, MEG3) in both FNAs and surgical tissues." (PMID 33030666, 2021). "Serum levels of MALAT1 have also been used as diagnostic and prognostic biomarkers in some other cancers." (PMID 34322395, 2021). "As a conclusion, our robust network-based framework has derived 31 AS-related lncRNAs that not only validates known cancer-associated cases MALAT1 and HOXA11-AS, but also reveals new players such as DNM1P35 and DLX6-AS1with potential functional implications." (PMID 32760422, 2020). "Here, we employed CRISPR to delete a short interspersed nuclear element (SINE) in Malat1, a cancer-associated lncRNA, to investigate its significance in cellular physiology." (PMID 31863590, 2020). "Metastasis-associated lung adenocarcinoma transcript 1 (MALAT1) is nuclear-enriched lncRNA that has attracted great attention due to its regulatory function in cancer." (PMID 31733641, 2020). "In cancer, the metastasis-associated lung adenocarcinoma transcript 1 (MALAT1), which regulates mRNA splicing, is the most studied cancer-associated lncRNA." (PMID 32492865, 2020). "Metastasis Associated Lung Adenocarcinoma Transcript 1 (MALAT1) is a highly abundant lncRNA in cancer and plays role in cancer development and progression." (PMID 32640630, 2020). "Another lncRNA whose expression is upregulated in multiple cancers is MALAT1 (metastasis-associated lung adenocarcinoma transcript 1)." (PMID 33291485, 2020). "Metastasis-associated lung adenocarcinoma transcript 1 (Malat1) is a 7.5-kb-long long intergenic noncoding RNA (lincRNA) transcript, which is associated with cancer progression and metastasis." (PMID 32321759, 2020). "In this study, we demonstrated the importance of a 148-bp SINEB1 element in Malat1, a cancer-associated lncRNA, in cell cycle regulation, cell survival, genomic stability, response to stress and TDP-43 proteostasis." (PMID 31863590, 2020). "Here, we report MALAT1 levels are differentially associated with the mesenchymal and amoeboid invasion mode, demonstrating its role in cancer cell invasion plasticity." (PMID 32369931, 2020). "Dysregulation of MALAT1 is associated with metastasis and the risk of tumor recurrence after treatment in various cancer types." (PMID 31479414, 2020). "LncRNA metastasis‐associated lung adenocarcinoma transcript 1 (MALAT1) is greatly overexpressed in multifarious cancers, including NSCLC." (PMID 33146951, 2020). "The long non-coding RNA Malat1 has been implicated in several human cancers, while the mechanism of action is not completely understood." (PMID 32050583, 2020).
cancer (continued). "Abnormal expression of lncRNA metastasis–associated lung adenocarcinoma transcript 1 (MALAT1) is reported in multiple human cancers, including prostate cancer, colorectal cancer, hepatocellular carcinoma, and HNSCC." (PMID 33123473, 2020). "One of the most studied lncRNAs in cancer is metastasis-associated in lung adenocarcinoma transcript 1 (MALAT1), as MALAT1 is highly expressed in cancer tissues and easily detected and functionally analyzed." (PMID 32174966, 2020). "Metastasis-associated lung adenocarcinoma transcript 1 (MALAT1) is a highly expressed lncRNA in many solid tumors and promotes cancer progression by regulating the alternative splicing and gene transcription." (PMID 32911687, 2020). "METTL16 was first found to have a close correlation with a cancer-promoting long non-coding RNA: metastasis-associated lung adenocarcinoma transcript 1 (MALAT1)." (PMID 33362863, 2020). "MALAT-1 has been identified in almost all types of human cancers and is associated with poor patient outcomes." (PMID 33052949, 2020). "Whereas cancer-associated polymorphisms have been recurrently identified within the MALAT1 gene locus, recent studies cast doubt on the ability of MALAT1 polymorphism data, alone, to establish a causative relationship between the lncRNA and human disease." (PMID 33329688, 2020). "MALAT1 was one of the primitively discovered cancer-associated lncRNA, also referred to as NEAT2 (Nuclear-Enriched Abundant Transcript 2)." (PMID 31792655, 2020). "In conclusion, this study elucidated the importance of the SINEB1 element in Malat1, a lncRNA implicated in many diseases from cancer to neurodegeneration." (PMID 31863590, 2020). "For example, lncRNA MALAT‐1 is up‐regulated in several cancers, causing poor prognosis of these cancer patients." (PMID 32596993, 2020). "Metastasis-associated lung adenocarcinoma transcript 1 (MALAT1) is one of the lncRNAs that is associated with human diseases and is a major player in the development and pathogenesis of various cancers." (PMID 33281877, 2020). "Another well-characterized lncRNA, metastasis-associated lung adenocarcinoma transcript-1 (MALAT1), has also been investigated as a potential adverse prognostic marker in the progression of many types of cancer." (PMID 32457731, 2020). "Here, we focus on one of the best characterized cancer-associated long non-coding transcripts, namely metastasis-associated lung adenocarcinoma transcript 1 (MALAT1)." (PMID 33375130, 2020). "High expression of MALAT1 is associated with poor prognosis of cancer patients, and closely correlated with tumor proliferation, autophagy, and drug resistance." (PMID 32802874, 2020). "Recent studies have shown that the long noncoding RNA metastasis associated lung adenocarcinoma transcript-1 (MALAT1) is associated with aggressive tumor phenotypes in different cancers." (PMID 31479414, 2020). "Taken together, these studies imply the MALAT1 is associated with cancer progression in various ways." (PMID 31792655, 2020). "The effect of lncRNA MALAT1 (metastasis-associated lung adenocarcinoma transcript 1) on the development and metastasis of various cancers, including OvCa, was shown in numerous studies." (PMID 33238475, 2020). "Among those lncRNAs, metastasis-associated lung adenocarcinoma transcript 1 (MALAT1), has been implicated in cancer signaling pathways." (PMID 32708561, 2020). "Metastasis-associated lung adenocarcinoma transcript 1 (MALAT1) is a commonly overexpressed lncRNAs in human carcinomas." (PMID 33126409, 2020). "MALAT1 is associated with tumourigenesis, apoptosis, and cell cycle progression in various carcinomas, including ATC." (PMID 33126409, 2020). "High levels of exosomal MALAT1, a long non-coding RNA associated to cancer metastasis, were observed in metastatic cases of OvC and were correlated to a poor outcome." (PMID 31167492, 2019).
cancer (continued). "One of the originally identified cancer-associated lncRNA was MALAT1 (Metastasis-associated lung adenocarcinoma transcript-1)." (PMID 31382922, 2019). "Metastasis-associated lung adenocarcinoma transcript 1 (MALAT1) was first identified as a member of the lncRNAs that is highly expressed in several types of cancer." (PMID 31413743, 2019). "LncACTdb 2.0 provides panels of comprehensive information including basic information, pan-cancer information, predicted and experimental information for the MALAT1-associating ceRNA interaction." (PMID 30476305, 2019). "Human metastasis-associated lung adenocarcinoma transcript 1 (MALAT1), an 8.7 kb lncRNA on chromosome 11q13, has been demonstrated to be overexpressed in several cancers." (PMID 31949884, 2019). "Recent studies have found that the MALAT1 gene polymorphism is associated with a susceptibility to various diseases, such as cancer risk and congenital heart disease." (PMID 31024342, 2019). "Metastasis-associated lung adenocarcinoma transcript 1 (MALAT1) is a lung non-coding RNA that is up-regulated in several cancers, including TC." (PMID 31412566, 2019). "For instance, MALAT1, one of the identified cancer-related lncRNAs, was reported to be closely associated with distant metastasis in NSCLC patients." (PMID 31889958, 2019). "With a working secondary structural model of human MALAT1, this study provides a platform to begin experimentally testing structure–function relationships potentially implicated in cancer and/or metastasis." (PMID 31717552, 2019). "Several lncRNAs have been identified as prognostic factors in cancers, such as metastasis-associated lung adenocarcinoma transcript 1 (MAlAT1) and cancer susceptibility 2 (CASC2)." (PMID 31227613, 2019). "The lncRNA MALAT1 (metastasis-associated lung adenocarcinoma transcript 1) is expressed in several cancers and is highly conserved in mammals." (PMID 31717266, 2019). "Metastasis-associated lung adenocarcinoma transcript 1 (MALAT1) is a well-known lncRNA associated with cancer angiogenesis and metastasis." (PMID 35582568, 2019). "MALAT1 (metastasis-associated lung adenocarcinoma transcript 1) is one of the first cancer-related lncRNAs that was originally recognized as a marker of survival and metastasis in patients with early stage NSCLC." (PMID 31818027, 2019). "Human metastasis-associated lung adenocarcinoma transcript 1 (MALAT1) is an abundant nuclear-localized long noncoding RNA (lncRNA) that has significant roles in cancer." (PMID 31717552, 2019). "Metastasis-associated lung adenocarcinoma transcript 1 (MALAT1) was up-regulated lncRNA in many tumors and associated with cancer cell metastasis and recurrence." (PMID 31014370, 2019). "MALAT1 (metastasis associated lung adenocarcinoma transcript 1), a well-studied lncRNA with intricate roles in the pathophysiology of cancer Metastases is one of such candidate." (PMID 29670884, 2018). "MALAT1 lncRNA has been associated with overexpression in various cancers and linked to unfavorable overall survival when overexpressed." (PMID 30416686, 2018). "Metastasis-associated lung adenocarcinoma transcript 1 (MALAT1) plays an important role in cancer and acts as a transcriptional regulator for various genes, including those involved in cell proliferation, migration, and metastasis." (PMID 30266744, 2018). "As its name suggests, MALAT1 has been associated with various pathological processes, particularly cancer, in which it regulates the expression of metastasis-associated genes." (PMID 29702599, 2018). "As a control, we also quantified expression of lncRNA MALAT1 (metastasis-associated lung adenocarcinoma transcript 1) known to be frequently upregulated in cancer." (PMID 30318443, 2018). "The high expression of MALAT1 in MM, along with its involvement in well-established cancer-associated pathways, points to a role of this lncRNA in MM pathogenesis." (PMID 29487387, 2018).
cancer (continued). "Many lncRNAs have been proved to associate with the prognosis of human cancers, such as metastasis-associated lung adenocarcinoma transcript 1 (MALAT1), HOXA transcript at the distal tip (HOTTIP), and growth arrest-specific transcript 5 (GAS5)." (PMID 30076198, 2018). "Metastasis-associated lung adenocarcinoma transcript 1 or MALAT1 is a ~7 Kb lincRNA that is evolutionarily conserved and is associated with many cancers." (PMID 30373256, 2018). "Our study showed that MALAT1 rs619586 A/G polymorphism was potential predictive biomarker of overall cancer risk." (PMID 29802154, 2018). "Metastasis-associated lung adenocarcinoma transcript 1 (MALAT1) is frequently overexpressed in malignant tumors and is considered as a biomarker for a variety of tumors." (PMID 29904151, 2018). "As an example, MALAT1 has been demonstrated to be associated with tumor stem regulation in several cancer types." (PMID 30223861, 2018). "Metastasis-associated lung adenocarcinoma transcript 1 (MALAT1) is a conserved lncRNA whose expression correlates with many human cancers." (PMID 29662883, 2018). "MALAT1 co-regulated genes on the other hand displayed only weak functional associations, and “Transcriptional misregulation in cancer” was the only identified KEGG pathway term." (PMID 29451908, 2018). "Different molecular mechanisms have been implicated in MALAT1 dysregulation in human cancer, and will be in-depth analyzed in the next paragraphs." (PMID 29739426, 2018). "The meta-analysis showed that MALAT1 rs619586 A/G polymorphism was associated with overall cancer risk." (PMID 29802154, 2018). "As a type of conservative LncRNAs, metastasis-associated lung adenocarcinoma transcript 1 (MALAT1) is highly expressed in multiple categories of cancer, including BC." (PMID 30459529, 2018). "Several studies revealed that MALAT1 has an elevated expression and was associated with a higher risk and poorer survival in many kinds of cancers." (PMID 29802154, 2018). "Among the top deregulated lincRNAs, three previously cancer associated lincRNAs—MALAT1, H19 and FENDRR, were significantly upregulated in a discovery cohort." (PMID 30557328, 2018). "We performed next-generation sequencing data analysis and validated expression of three deregulated and cancer associated lincRNAs–MALAT1, H19 and FENDRR–in GIST and adjacent tissues." (PMID 30557328, 2018). "While the precise role of Malat1 in cancer is still not fully understood, a number of studies indicate that Malat1 frequently functions as an oncogene and is associated with metastasis and poor prognosis." (PMID 29912916, 2018). "MALAT1 is known to be upregulated in many cancers and associated with poor survival and tumour growth." (PMID 30205577, 2018). "MALAT1 is overexpressed in various cancers and linked to promotion of radioresistance through triggering EMT, CSC activity, and anti-apoptosis ability." (PMID 28872613, 2017). "Two meta-analyses of 10 studies on MALAT1 in various cancer types indicated a relatively consistent association of increased MALAT1 expression with survival in various types of cancer, but some studies analysed only few cases." (PMID 28430799, 2017). "High MALAT1 expression was also associated with high stage, metastasis and shorter overall survival after radical nephrectomy and chemotherapy in cancer patients." (PMID 29290978, 2017). "This study seek to meta-analyze the overall diagnostic efficacy of elevated MALAT-1 expression profile for human cancers." (PMID 29254244, 2017). "MALAT1 up-regulation has been observed in various types of cancer, where it is associated with tumorigenesis and a decrease in overall survival." (PMID 28637507, 2017). "Several studies showed the aberrant expression of MALAT1 in tumour tissues compared with normal tissues and its association with clinical progression in human cancers, suggesting an important role in cancer pathogenesis and progression." (PMID 29156758, 2017).